RNU6-37P (RNA, U6 small nuclear 37, pseudogene)
Synonyms: RNU6-37
Gene: Small nuclear RNA gene on chromosome 1 (10,298,966 to 10,299,072, forward strand). Ensembl gene ENSG00000199562.
Homologues: Orthologues: dog U6 (100% identical), macaque U6 (100% identical), rat U6 (100% identical), pig U6 (98% identical). Paralogues in human: RNU6-11P (100% identical), RNU6-1 (98% identical), RNU6-2 (98% identical), RNU6-3P (98% identical), RNU6-4P (98% identical), RNU6-5P (98% identical), RNU6-6P (98% identical), RNU6-7 (98% identical), RNU6-8 (98% identical), RNU6-9 (98% identical), RNU6-12P (97% identical), RNU6-13P (97% identical), and 1289 more.